APEX1 (apurinic/apyrimidinic endodeoxyribonuclease 1)
Diseases named in the same sentence as APEX1 in open-access papers (continued):
Sharing a sentence is not in itself a finding about the gene and the disease.
cancer (continued). "The conflicting association between APEX1 gene polymorphisms and cancer risk may be explained by the differences in the sample sizes, race, cancer types, selection criteria for subjects, and environmental exposures." (PMID 31341530, 2019). "However, none of these variables were observed to significantly affect the relationship between the APEX1 Asp148Glu polymorphism and cancer susceptibility." (PMID 24349526, 2013). "Thus, aberrant expression of the APEX1 gene may compromise the proper functioning of vital cellular processes, potentially elevating an individual's susceptibility to cancer." (PMID 40833230, 2025). "Finally, this study may aid in our understanding of potential hematopoietic side effects associated with the use of APEX1 inhibitors in cancer therapy and suggests a possible beneficial therapeutic use of E3330 in interferonopathies." (PMID 37266894, 2023). "Furthermore, many studies have suggested increased APEX1 levels to be diagnostic and prognostic for cancer, and that APEX1 may be a therapeutic target for treatment of advanced cancer." (PMID 35780128, 2022). "The APEX1 gene is highly polymorphic in cancer patients and has a role in the accumulation of the apurine/apyrimidine site in DNA and consequently may lead to an increased risk of cancer development." (PMID 33809336, 2021). "Therefore, we suggest that s-APEX1 expression could be a suitable diagnostic tumor marker for the three cancers." (PMID 31375000, 2019). "In terms of the relevance of APEX1 to cancers and neurodegenerative diseases, we refer readers to recent excellent reviews." (PMID 40243693, 2025). "It has been reported that APEX1 plays a key role in the progression of a variety of cancers, including gastric, colon, and hepatocellular carcinoma." (PMID 38360860, 2024). "APEX1 promotes multidrug resistance in cancer, enhances KAT6A LLPS, and facilitates interaction between KAT6A and PARP1." (PMID 38973255, 2024). "We also contrasted these findings with APEX1 KD in various human cancer cell types to highlight the unique and shared therapeutic potential of APE1 in ocular diseases." (PMID 36674619, 2023). "Cancer cell line studies demonstrated that APEX1 is indispensable for cancer cell survival and proliferation." (PMID 37266894, 2023). "This is in contrast with the gene regulation patterns frequently seen in cancer cells with APEX1 KD." (PMID 36674619, 2023). "APEX1 expression presents up-regulated in several human cancer types, which is correlated to aggressive clinicopathological parameter and poor prognosis of these cancer 23, 28-30." (PMID 37283798, 2023). "Nonetheless, the findings of this study are enlightening since few studies have knocked down APEX1 in primary cells such as HRECs as most studies have been done in transformed cancer cell lines." (PMID 36674619, 2023). "APEX1 inhibitors or knockdown of APEX1 expression to promote tumor cell death by regulating the ferroptosis pathway can be utilized in the treatment of cancer." (PMID 35311089, 2022). "In other words, APEX1 has the potential to regulate cancer, nervous system diseases, and other diseases through ferroptosis." (PMID 35311089, 2022). "Aberrant expression of APEX1 has been frequently identified in cancers and plays crucial roles in the modulation of multiple oncogenic properties." (PMID 36205565, 2022). "To accomplish this aim, we assessed the relationships among APEX1, cellular proliferation, apoptosis regulation, and cancer progression through specific signaling pathways." (PMID 35780128, 2022). "A positive correlation between the expression of APEX1 and MAP2K6 was noted, and overexpressing MAP2K6 overcame cancer-related phenotypes associated with APEX1 silencing." (PMID 36205565, 2022). "In summary, we have produced two APEX1 null derivatives of the commonly used HEK 293FT human non-cancer cell line and characterized them at the genetic, biochemical and phenotypic level." (PMID 34529719, 2021).
cancer (continued). "APEX1 is overexpressed in many cancer cells, including cervical, ovarian, and prostate cancer cells and myeloma cells, and its altered level or intracellular distribution has been found in various cancers." (PMID 33525741, 2021). "To facilitate studies of multiple functions of this protein in human cells, we have used the CRISPR/Cas9 system to knock out the APEX1 gene in a widely used non-cancer hypotriploid HEK 293FT cell line." (PMID 34529719, 2021). "Here we report the generation and characterization of a CRISPR/Cas9 APEX1 knockout in the extensively studied non-cancer HEK 293FT human cell line." (PMID 34529719, 2021). "Interactions of APEX1 and the metastasis mechanism of related proteins have been reported in several malignant tumors." (PMID 33946672, 2021). "Since APEX1 is highly expressed in cancer cells and has been served as a biomarker for LC and other cancers, targeting APEX1 is therefore a promising strategy in the search of new anticancer treatments." (PMID 33990544, 2021). "Previous studies have shown that APEX1 is actively involved in the DNA damage response in lung and prostate cancers." (PMID 32167932, 2020). "Apex1 is an excellent marker for rapid proliferation in cancer cells including glioma, prostate, head and neck, pancreas, colon and breast." (PMID 31024003, 2019). "As APEX1 serum level has been reported to be increased also in various types of cancers serum APEX1 level should be used in combination with other diagnostic tools, such as ultrasonography and CT/MRI imaging for the diagnosis of CCA." (PMID 31454981, 2019). "We demonstrated that the s-APEX1 level was significantly higher in patients with the three cancers than in the healthy control group, while the serum level of individuals in the HBV DNA (+) group was higher than those with three cancers." (PMID 31375000, 2019). "Little is known about the mechanism or influence of extracellular secretion of APEX1 in the three cancers and under inflammatory conditions." (PMID 31375000, 2019). "The APEX1 stimulates numerous transcriptional factors that are involved in cancer promotion and progression, such as HIF-1α, nuclear factor kappa B (NFκB)." (PMID 31454981, 2019). "Recently, APEX1 has been regarded as a target for cancer therapeutics because its high expression have been found to be related to resistance to radiotherapy, chemotherapy and poor survival in a general spectrum of cancers." (PMID 31827400, 2019). "Similar to flavanones, nodes such as CYPs in module 1 and APEX1 in module 2 were also detected in flavanonol, which indicated the potential function of it on cardiovascular and cancer related functions." (PMID 30158870, 2018). "Polymorphisms of MLH1, APEX1, MUTYH, OGG1, NUDT1, and XRCC5 are associated with sporadic CRC and other site‐specific cancers." (PMID 29664240, 2018). "As a component of the DNA repair machine and redox-sensitive transcriptional cofactor for NF-κB, HIF-1, and AP-1, APEX1 has a primary role in early embryonic development, tissue aging, and a wide spectrum of diseases, including cancers, neurodegenerative diseases, and cardiovascular diseases." (PMID 40243693, 2025). "APEX1 also presents a potential target for drug therapy in certain cancer types." (PMID 40833230, 2025). "APEX1 is involved in the progression of some human cancer types." (PMID 37283798, 2023). "In addition, simultaneous knockdown of both circCIMT and APEX1 promotes the expression of cancer‐related genes and malignant transformation after long‐term Cd exposure." (PMID 36814305, 2023). "The APEX1 overexpression is correlated with cancer progression in various human solid malignancies." (PMID 35780128, 2022).
cancer (continued). "Additional studies in other cancer types may be investigated to test whether the modulation of AS by targeting APEX1 could be broadly applied as novel therapeutic strategy for cancer." (PMID 35780128, 2022). "Therefore, it was necessary to study the intrinsic mechanism of APEX1 on cancer cell proliferation or apoptosis." (PMID 35780128, 2022). "Furthermore, APEX1-regulated AS of many genes, which were related to cancer proliferation and apoptosis pathways." (PMID 35780128, 2022). "Because cancer tissues are complicated by multiple cell types and deregulated genes, these potential APEX1-RASEs could contribute to oncogenesis." (PMID 35780128, 2022). "The APEX1 may play a role in promoting cancer by inducing the expression of many oncogenes, although identification of the precise mechanism requires further study." (PMID 35780128, 2022). "Therefore, it is worthwhile to explore the role of APEX1 in regulating ferroptosis, especially in the area of cancer." (PMID 35311089, 2022). "However, the involvement of APEX1 in cancer progression, especially its impact on genes within functional signaling pathways, has not been fully elucidated." (PMID 35780128, 2022). "In addition, we confirmed that APEX1 regulated the AS of key tumorigenesis genes involved in cancer proliferation and apoptosis pathways, mediating NSCLC progression." (PMID 35780128, 2022). "The mechanism could be that APEX1 regulated AS of key tumorigenesis genes involved in cancer proliferation and apoptosis within the MAPK and Wnt signaling pathways, including genes encoding kinases and transcription factors." (PMID 35780128, 2022). "In addition, by qPCR and RNA-seq we identified several cancer-related genes that regulated by AS of APEX1, which included AXIN1, GCNT2, SMAD3, CTBP2, PPARD, and FBXW11." (PMID 35780128, 2022). "Forty cancer samples were selected from 20 high and 20 low APEX1 expression samples." (PMID 35780128, 2022). "In addition, APEX1 regulated AS of key tumorigenesis genes involved in cancer proliferation and apoptosis within MAPK and Wnt signaling pathways." (PMID 35780128, 2022). "Involvement of APEX1 in tumor metastatic mechanisms has been shown in many cancers, but its role and mechanism in CCA remains unclear." (PMID 33946672, 2021). "To elucidate whether APEX1 and related proteins play a role in cancer progression, we evaluated the protein expression levels of APEX1 and related proteins." (PMID 33946672, 2021). "The APEX1 gene is relatively small and is not highly mutation prone like some genes, but a few mutations have been noted in cancers that result in persistent genomic stress." (PMID 34541539, 2021). "In some cancers, APEX1 is aberrantly expressed and activates the Notch signaling pathway." (PMID 32167932, 2020). "APEX1 is a multifunctional protein which plays a fundamental role in DNA repair and redox signaling by activating proteins involved in cellular response to several stresses such as inflammation and cancer." (PMID 28068390, 2017). "The up-regulation of APEX1 mRNA was also reported in sheep B lymphocytes transfected with Tax-containing vector, and in tumor tissues and cancer cells of diverse origin, and its overexpression is associated with tumor cells’ resistance to various anticancer drugs." (PMID 27812893, 2017). "Notably, RYR1 and APEX1 are the targets of two FDA-approved cancer drugs (caffeine and lucanthone, respectively)." (PMID 27788148, 2016). "Additionally, other signaling axes, e.g., signal-regulated kinase (ERK)/mitogen-activated protein kinase (MAPK), Metadherin (MTDH), apurinic/apyrimidinic endonuclease-1 (APEX1), etc., also coordinate with each other to promote cisplatin resistance in different cancers." (PMID 40149331, 2025). "However, the clinical significance and concomitant role of APEX1 in cancer remains unclear, although APEX1 has been shown to be a positive regulator, contributing to the aggressive behavior of cancer behaviors." (PMID 35780128, 2022).
cancer (continued). "Therefore, APEX1 may be a promising target to treat cancer and nervous diseases by regulating ferroptosis." (PMID 35311089, 2022). "It was determined that APEX1 in cancer can increase the ROS level due to an unknown mechanism." (PMID 33990544, 2021). "Therefore, APEX1 has been studied and worked as a biomarker for a variety of cancers." (PMID 33875645, 2021). "Additionally, cytoplasmic APEX1 expression in cancer cells could be used to predict relapses in patients with HCC or CC." (PMID 31375000, 2019). "Apurinic/apyrimidinic endodeoxyribonuclease 1 (APE1) is a multifunctional protein involved in DNA repair, transcriptional regulation, and redox signaling, which significantly contributes to cancer progression and chemoresistance." (PMID 41870991, 2026). "In the proteomic cluster featured with the high cell proliferation rate, APEX1 and NPM1 are found to promote cell proliferation and drive the progression of cancer cells." (PMID 38360860, 2024). "After examining the pulled‐down proteins by lncRNA ARHGAP5‐AS1 using mass spectrometry proteomics, we identified multiple cancer‐related proteins including CSDE1, ZC3HAV1, CCT8, CKAP4, PARP1, PEG10 and APEX1 in HepG2." (PMID 36354136, 2022). "High levels of APEX1 (apurinic/apyrimidinic endodeoxyribonuclease 1) and PARP1 (poly(ADP-ribose) polymerase 1), involved in base exchange repair (BER), confer chemoresistance in several types of cancer." (PMID 33918653, 2021). "Our results reveal three important genes, HMGB1, APEX1, and POLE3, that function in the epigenetic control of a DNA-repair mechanism, which modulates cancer in HT29 cells, and induce apoptosis." (PMID 34500845, 2021). "Additionally, the TISCH2 indicated that all the hub-genes of cancer cells were upregulated in malignant cells, especially GAPDH, RHOA, TPI1, H4C6, DDX21, and APEX1, which showed considerably high expression levels in malignant cells." (PMID 40906153, 2025). "Furthermore, the MYC, DDX21, USP7, RFC4, APEX1, CDK9, and NOP2 of the “cancer cells_vs_all-PDAC” group play a critical role in the metabolic reprogramming of the PDAC, contributing to the poor prognosis of PDAC." (PMID 40906153, 2025). "The protein network of unique cancer cell genes in the “cancer cells_vs_all-PDAC” group exhibited top 10 hub genes, including H4C6 (HIST1H4A or HIST1H4C), MYC, H3C12 (HIST1H3A or HIST1H3D), DDX21, USP7, RFC4, APEX1, CDK9, H2BC9 (HIST1H2BH), and NOP2." (PMID 40906153, 2025). "We investigated the immunohistochemical levels of APEX1 in cancer and paracancerous tissues of 20 patients with pathologically confirmed LUAD and confirmed that the APEX1 level in tumor tissue was higher than that in paracancerous tissue, which is in line with other studies reported." (PMID 40495893, 2025). "APEX1 is known to have a multifunction, as it facilitates the BER pathway in repairing damaged DNA, and it also acts as a co-activator for several transcription factors, which are involved in cancer promotion and progression." (PMID 36287252, 2023). "have reported that APEX1 interacts with HIF-1α under hypoxia and inhibition of APEX1 will result in decreased HIF-1α–mediated induction of carbonic anhydrase IX, which will inhibit viability of cancer cells." (PMID 35311089, 2022). "Over expression of APEX1 has been described in NSCLC and other cancers, while its down-regulation may induce apoptosis." (PMID 27799870, 2016). "The human apurinic/apyrimidinic endodeoxyribonuclease 1 (APE1) is responsible for the protection of cells against genotoxins and for safeguarding genome stability as the main AP-endodeoxyribonuclease of the BER pathway playing a pivotal role in cancer chemoresistance." (PMID 35876890, 2022). "Besides common nodes such as CYPs, APEX1, MAPT, which reflect the same function for cancer, cardiovascular and neurodegenerative as other flavonoid subclasses flavones contains other nodes such as ALDH1A1 in module 5, which reflect potential associations with cancer invasion." (PMID 30158870, 2018).
cancer (continued). "Also, after systemically analysis of targets for different flavonoids subclasses, it can be found that targets such as MAPT, APEX1, and ALDH1A1, which were closely related with nervous system and cancer, were significantly enriched in almost all flavonoid subclasses." (PMID 30158870, 2018). "We also found enrichment of APEX1 neighbors for “PI3K-Akt signaling pathway” (KEGG pathway, P = 5.01e-04) and “regulation of gene expression by hypoxia-inducible factor” (Reactome pathway, P = 5.49e-05), both of which are well known cancer therapeutic target signaling pathways." (PMID 27333808, 2016). "Furthermore, in a spectrum of human tumors, including breast, thyroid, or glioblastoma malignancies, immunoreactivity of APEX1 in cancer tissues has a negative correlation with senescence, although there is no clarification on which tissue types, i.e., tumor, stroma, or immune cells, are senescent." (PMID 40243693, 2025). "In this study, we explored associations between genotypes of base-excision repair genes (PARP1 Val762Ala, APEX1 Asp148Glu, and XRCC1 Arg399Gln) and in vitro BPDE-induced DNA adducts in cultured peripheral blood lymphocytes in 706 cancer-free non-Hispanic white subjects." (PMID 22792228, 2012). "Another subgroup of PPIs presumably perturbed by cancers is characterized by negative or near-zero r-values in cancers and positive r-values of gene co-expression in conditionally normal tissues, for example, C1orf131/EIF3L, C19orf53/APEX1, C1orf198/PPP2R1A and C1orf198/ARHGEF1." (PMID 37373333, 2023).